CD44 (CD44 molecule (IN blood group))
Diseases named in the same sentence as CD44 in open-access papers (continued):
Sharing a sentence is not in itself a finding about the gene and the disease.
cancer (continued). "In this study, which has used THP-1 cells or blood monocytes, physical co-culturing of monocytic cells with cancer cells has given rise to elevated proportions of CSCs (CD44+/CD24− and ALDH+) and the cancer cells have gained some EMT characteristics." (PMID 33585241, 2020). "Taken together, these findings indicate that the promotion of metastasis, stem cell-like phenotype, and chemoresistance involves intracellular cooperation between CD44 and STAT3 on a molecular level across numerous cancer models, including ovarian." (PMID 33335857, 2020). "Although the molecular definition of CSCs in HCC is still emerging such as CD24, CD44, CD90 and EPCAM7,8, three transcription factors, Oct4, Nanog and Sox2, have been strongly identified as master regulators of cancer stemness." (PMID 32024815, 2020). "In EMT, ESRP1 was thought to directly regulate these subtypes such as FGFR2, ENAH, CD44 and CTNND, thereby losing cell-to-cell adhesion and polarity, increasing cancer cell invasion and migration." (PMID 32467669, 2020). "The overexpressing h-jou transfected cells were also enriched in potential cancer stem cell (CSC) markers, including SOX4, SOX8, CD44, MSI-2, EpCAM, and others." (PMID 33225905, 2020). "Cancer stem cell markers ALDH1A2, ALDH7A1, CD44, and CCND1 were also upregulated in CTCs compared to HDs." (PMID 32998338, 2020). "WB results showed that the expression of the cancer stem cell markers ALDH1A1, CD44, and Nanog was upregulated when cells were stimulated with LY CM, but this upregulation was diminished when cells were treated with LY + Met CM." (PMID 33116117, 2020). "Third, cancer stem cells (CSCs), a continuously proliferating subset of cancer cells with stem-like and tumor cell characteristics, express, among other markers, CD24, CD44, and CD133, and they increase tumorigenic potential and drive growth and metastasis." (PMID 33260974, 2020). "Hyaluronic acid (HA) is the main ligand for CD44, which is a constituent of the extracellular matrix (ECM) and it is expressed by stromal and cancer cells." (PMID 33093503, 2020). "IGF2BP1 stabilizes the CD44 mRNA through binding to its 3′-UTR, and thereby contributes to cellular adhesion and invasion during cancer development and formation." (PMID 32967226, 2020). "In our study, stem cell markers (CD44, CD24 and CD133) decreased after SPNs induction in MIA PaCa-2 cancer cells." (PMID 32489562, 2020). "For targeted cancer therapy, attempts have been made to generate conjugates of membrane incorporating molecule DSPE-PEG200 and Hyaluronan (HA), a CD44-specific ligand, which are then self-assembled into the phospholipid bilayer of milk exosomes." (PMID 33023062, 2020). "Considering the intimate connection between EMT and cancer stemness, we further examined the expression of six key biomarkers of cancer stemness (NANOG, SOX2, OCT4, CD44, ABCG2, BMI1)." (PMID 32863941, 2020). "Next to in vitro propagation as spheres, cancer stem cell markers like prominin-1 (CD133) and CD44 antigen (CD44) are frequently used to identify cancer stem cells in CRC." (PMID 32927768, 2020). "SRGN has been shown to promote cell migration in several types of cancer, and SRGN promoted NSCLC cell migration in a CD44-dependent manner." (PMID 31898491, 2020). "Some specific markers are over-expressed on the membranes of cancer cells, such as integrin αvβ3, CD44 and receptors of transferrin, folic acid and galactose, the ligands of which could be grafted onto the surface of gas-releasing nanomedicines to recognize cancer cells." (PMID 34691545, 2020). "The findings revealed that ALDH, CD24, CD44, and CD90 were highly expressed in the isolated cancer stem cells." (PMID 32314522, 2020). "Compared with CD83-OV and control groups, CD83-KD cancer cells showed a reduction of stemness factors, including KIT, CD44, and SOX2." (PMID 32823589, 2020).
cancer (continued). "Taken together, these data show that CD44 enhances GBM tumorigenesis via radioresistance with a hyperactive DDR, escaping from apoptotic cell death, cancer stem‐like properties, angiogenesis, and cell proliferation." (PMID 31746135, 2020). "As CD44 only showed a positive correlation with EPHB3 among the candidate CSC markers we examined, it would be interesting to explore the interplay between CD44 and EPHB3 and its effect on cancer stem cell biology in CRCs in future studies." (PMID 32294981, 2020). "Consistently with the higher level of CD44, an established marker of stemness in OSCCs 24, UPCI-SCC-131 cells exhibited higher expression of the cancer stem cell marker, Lgr5 25-26 compared to HPV-positive UPCI-SCC-154 cells." (PMID 31929745, 2020). "The purpose of this study was to investigate the in vivo therapeutic efficacy of CD44-targted NIR-PIT and IL-15 treatment in syngeneic mouse models of cancer compared to either therapy alone." (PMID 32927646, 2020). "Previously, it was reported that PTE suppresses the expression of CD44, c-Myc, and cyclin D, and hedgehog/AKT signal, which preferentially damages cancer stem cells." (PMID 33302440, 2020). "CD44, a surface marker for cancer stem cells, interacts with PKM2, a key regulator of aerobic glycolysis, and enhances the glycolytic phenotype of cancer cells leading to antioxidant protection and macromolecules’ synthesis." (PMID 32326107, 2020). "Cancer cells sense ECM components and their mechanical properties by multiple adhesion and signal-transducing receptors, including integrins, syndecans, or CD44." (PMID 33321819, 2020). "CD44 and CD24 expression, as cancer stem cell markers, were elevated in only WT liver with CCl4 administration." (PMID 33168815, 2020). "PCSCs express markers of cancer stem cells (CSCs) including CD24, CD133, CD44, and epithelial specific antigen as well as the drug transporter ABCG2 grow as spheroids in a defined growth medium." (PMID 34841087, 2020). "The levels of cancer stemness-related genes (ABCG2, BMI1, NANOG, KLF4, and OCT4) mRNA and proteins (ABCG2, Oct4, Bmi-1, and CD44) expression were downregulated with treatment of STF-31 in HBx-expressing MHCC-97H cells." (PMID 32168902, 2020). "In cancer cell line models CD44+ cells demonstrated significantly elevated MMP-2 and MMP-9 levels compared to CD44- cells, further indicating that CD44 is involved in MMP-2 and MMP-9 expression." (PMID 33335857, 2020). "By using different parameters to evaluate biomarkers of cancer stemness, such as overexpression of CSC markers, elevated CD44/CD24 ratios, self-renewal capabilities and high invasion potentials, we found that JQ1 can jeopardize stemness in TNBC." (PMID 32166583, 2020). "Several markers of cancer stem cells have been identified that include CD44, CD117 and CD133, which have been widely utilized for the characterization and downstream interrogation of these cancer stem cell population." (PMID 32046162, 2020). "For instance, in many cancers including CRC, alternative spliced CD44 (CD44v, retained form) promotes apoptosis resistance, DNA damage resistance." (PMID 31964396, 2020). "The purpose of this study was to investigate the in vivo therapeutic efficacy of the combination of CD44-targeted NIR-PIT and CTLA4 blockade in several syngeneic mouse models of cancer." (PMID 32937841, 2020). "Compared to control cells, OSCC cells in which UBE2C was silenced showed decreased cell proliferation, migration/invasion and colony formation and they exhibited lower expression levels of the following cancer stemness markers—ALDH1/A2, CD44, CD166 and EpCAM." (PMID 32899896, 2020).
cancer (continued). "Our results consistent with these reports and indicated that SPP1 has a more important correlation with CD44 and ITGB1 in selected cancer contrast to adjacent normal tissue." (PMID 33324676, 2020). "TNBC cancer stem cells (CSC) feature enhanced proliferative capacity, refractory treatment which leads to recurrence and metastasis (CD-24, CD-44)." (PMID 32245065, 2020). "We show quantitative analysis of filopodia in three human cancer cell lines with induced expression of HAS3, CD44, and variable hyaluronan synthase activity by manipulating the levels of sugar precursors for hyaluronan building blocks." (PMID 32679746, 2020). "Thus, CD44-ICD could be a useful biomarker of cancer progression." (PMID 33062960, 2020). "Therefore, CD44 may act in concert with αvβ3 integrin to home cancer cells to bone." (PMID 32527062, 2020). "Cancer stemness induced via up-regulation of ALDH1A1 and CD44 expression contributes to the acquisition of gefitinib resistance in EGFR-TKI sensitive NSCLC." (PMID 32293355, 2020). "Thus, the absence of stromal cells in our experimental model may explain the lack of measurable increase in CD44 levels similar to what was observed in those cancer-associated desmoplasias." (PMID 32435546, 2020). "Aberrant alternative splicing produces CD44 isoforms that are overexpressed in carcinomas, including GAC, whereas the standard CD44 isoform is predominantly expressed in normal cells." (PMID 32751679, 2020). "All six PCC cultures demonstrated a strong expression of pan-CD44, consistent with previously reported data in human PDAC-derived carcinoma cells." (PMID 31963309, 2020). "AKT/PI3K signaling being activated by CD44 and CD133 is essential for maintenance of cancer stemness in PCa cells." (PMID 30935014, 2019). "Treatment of cancer cells with c-Src inhibitor, PP2, or Twist siRNA significantly blocks the production of HA/CD44-mediated miR-10 expression and downstream RhoGTPase (RhoC)-ROK effector functions." (PMID 31293964, 2019). "Consistently, irradiated feeder cells induced CD133− cancer cells to form more spheres, which also presented higher levels of CSC markers CD133 and CD44." (PMID 31558702, 2019). "CD133 and CD44 are two stem cell markers, while SOX2 and Nanog are two transcription factors involved in the maintenance of cancer stem-like cell properties." (PMID 31130822, 2019). "The primary cultured cells derived from the malignant tumors and metastatic nodules sustained the expression of stemness markers, such as Nanog, Klf4 and c-Myc, and acquired cancer stem markers, such as CD90, CD44 and ALDH1." (PMID 31450740, 2019). "In cancer cells, the CPT-HA-NPs showed dose-dependent cytotoxicity, but their cytotoxicity was highly reduced in normal cells with low CD44 expression." (PMID 31072061, 2019). "The weak fluorescence in cells was due to the fact that the CD44 receptor on cancer cells was occupied by free HA, resulting in a decrease of binding capacity between DOX@CDHA–MGO and CD44." (PMID 30960117, 2019). "To further validate that HT29 colonospheres are stem-like spheroid cells, we tested the expression level of CD44, which is a putative marker of CRC cancer stem cells." (PMID 31131257, 2019). "We identified 156 focal amplifications and 69 focal deletions, in well-known oncogenes, such as ERBB2, CCNE1, KRAS, MYC, EGFR, and CDK6, and cancer-related genes such as GATA4, GATA6, CD44 and ZNF217." (PMID 31570735, 2019). "In order to study possible changes in putative cancer stem cell markers due to HNE-pretreated collagen and due to multiple HNE treatments, the expression of CD44, CD24, and ALDH was assessed." (PMID 31835715, 2019). "Cancer stem cells (CSCs) were quantified by flow cytometry usinganti-CD24-FITC and anti-CD44-APC antibodies and propidium iodide." (PMID 31384244, 2019). "According to a univariate analysis, higher N and cancer stages, extrathyroidal involvement, and CD15, CD44, CD166, and ALDH1A1 positivity were related to a shorter PFS." (PMID 31428052, 2019).
cancer (continued). "Considering the complexity and heterogeneity of CSCs, TSPAN8 can be used as a molecular marker in combination with other CSCs markers, such as ALDH1 and CD44+/CD24−, to define cancer cell stemness." (PMID 31253779, 2019). "Overall pooled analysis suggests that high expression of CSC markers (including CD133, CD44, CXCR4, and CD105) predicts poor overall survival, cancer-specific survival, disease-free survival, and progression-free survival." (PMID 30796200, 2019). "These ECMR pathways were associated with a significantly increased expression of genes involved in the CXR/CCL chemokine pathway, including CD44 and CXCR4 which are cancer stem-cell markers." (PMID 31874999, 2019). "Western blot also showed that the expressions of CD44 as well as ALDH1A1, which is another well-known cancer stem cell marker, were repressed in HCC827OR and HCC827GR cells treated with aspirin." (PMID 31993373, 2019). "Thus, the alternative splicing of CD44 is often deregulated in cancers, and produce various isoforms with properties that may have different tissue specific effects and therefore even diverse effects on cancer progression." (PMID 31857793, 2019). "PDAC cancer cells are composed of different subpopulations, such as epithelial cancer cells, CD24+/CD44+ cancer stem cells, CD133+ cancer stem cells, and mesenchymal cancer cells; furthermore, each cell population is genetically heterogeneous." (PMID 31275385, 2019). "ALDH1A3, CD44, and MDR1 were found to play a role in the cancer cell resistance to FAK autophosphorylation inhibitor Y15 and their downregulation would sensitize resistant cancer cells to Y15." (PMID 31368612, 2019). "Some of these resistance mechanisms, specifically the over-expression of ABCB1 and CD44 molecules among others, develop because of WNT signaling pathway deregulation in the cancer stem cell subset." (PMID 31921125, 2019). "Cells positive for SERPINB2 were also largely positive for CD44, CD133 or ALDH in each cancer tissue sample." (PMID 30965654, 2019). "We focused on the genes TNFRSF12A, CD44 and NFKB2 in more detail given their role in the multiple cellular pathways and cancer and the high scoring of the corresponding switching events." (PMID 30857150, 2019). "This process initiates the transcription of downstream genes (e.g., CD44, VEGF, c-Myc, and cyclin D1), leading to the proliferation of cancer cells and occurrence and development of tumors." (PMID 31827404, 2019). "CSC have been isolated from nearly every human cancer through identification of surface marker expression of nearly 40 different markers which vary from cancer to cancer (CD133, CD44, CXCR4, CD90, etc.)." (PMID 32355893, 2019). "Both Meta3 and Meta4 cells have high expression of many key markers of metaplasia, such as Wfdc2, Mal2, and Gpx2, and cancer stem cell (CSC) marker genes, such as Cd44, CD133 (Prom1), and CD166 (Alcam)." (PMID 31804471, 2019). "The results showed that after sphere culture, the spherical cells express higher levels of CD24, CD44, and CD133 than HT-29 cancer cells." (PMID 30770752, 2019). "To identify the cancer stem cell (CSC) subpopulation, we analyzed expression ofthe markers CD44 and CD24 by flow cytometry." (PMID 31384244, 2019). "Cell viability, proliferation, apoptosis and the expression of different cancer stem cell markers (CD133, CD24, CD44, CD29, CD73 and CD105) were analysed." (PMID 31371743, 2019). "CSCs have been extensively studied in many cancers, with ALHD1, CD44, and CD133 among the most investigated CSC markers." (PMID 30999901, 2019). "Studies of neoplastic tissues have provided evidence of stem-like cells within tumors, of breast (CD44+CD24−/low), pancreatic (CD44+CD24+ESA+), brain (CD133+), head and neck (CD44+), and colon (CD133+ and CD44+ESAhigh) cancer." (PMID 30959764, 2019). "CD44 is one of the most common CSC surface markers, used either alone or in combination with other putative markers, to identify CSCs in OC and other cancers." (PMID 31277278, 2019).
cancer (continued). "Assessment of known cell stemness biomarkers DPP4, CD44, MSI1 and ALCAM as well as autofluorescence showed that resistant cells are enriched with cancer stem cells." (PMID 31336714, 2019). "The cancer-favoring oncolytic vaccinia virus’ selective infection and therapeutic efficacy against stem-cell-like colon (CD133+ and CD44+) cancer cells in combine with fluorouracil were reported in colon cancer." (PMID 30841635, 2019). "HCT116 cell line was identified as cancer stem-like cells with the high expression of CSCs markers CD133 and CD44." (PMID 31640758, 2019). "So, we treated resistant cancer cells with aspirin and then examined the expression of CSC markers CD44 by immunofluorescence analysis." (PMID 31993373, 2019). "These cells expressed cancer stem cell (CSC) -related characteristics, including the ability to form spheroids, the expression of the CD44 marker, and the increase of protein stability." (PMID 31717306, 2019). "Thus, HA could be an ideal biomaterial for CD44-over-expressing cancer cells." (PMID 31266194, 2019). "Mice were subcutaneously immunized with the repeat cycles of freezing and thawing whole HO8910 CD117+CD44+ CSCs and ID8 cancer stem-like cells, respectively, followed by a challenge with HO8910 or ID8 cells at one week after final vaccination." (PMID 31008116, 2019). "It has been reported that CD44, CD133, ALDH (Aldehyde dehydrogenase), CD271, CD90, and Side-population (Hoechst 33,342 dye exclusion) are potential biomarkers used to identify cancer stem cells in ESCC." (PMID 30979011, 2019). "The correlation coefficient between the expression level of cancer stem cell markers ALDH1A1, CD44, OCT3/4, and ABCG2 with the stages of PTC tumors as well as TFA samples was calculated." (PMID 31341476, 2019). "We isolated CD44+/CD24- cells from the normal cancer cells with MACS and detected CD44 and CD24 expression to determine CD44 purity by flow cytometry." (PMID 31612865, 2019). "There are only a few aptamers against stem cells markers such as cancer stem cells (CSCs), including cancer cell surface biomarkers: Epithelial cell adhesion molecule (EpCAM), CD133, CD117, and CD44, and those for mouse embryonic stem cells." (PMID 30866536, 2019). "CD44, as the most frequently reported CSC marker, is widely used to distinguish CSCs from other populations of cancer cells." (PMID 31497537, 2019). "CD44 activates hypoxia-inducible HIF-1α signaling via the ERK pathway, and this signaling is responsible for increased cancer cell viability and motility under hypoxic conditions." (PMID 30970626, 2019). "CD44 expression decreased by 15% (p < 0.05) in the THYME 1 group and ALDH1A1 expression by 27% (p < 0.05) in the THYME 0.1 group versus the control rat carcinoma cells." (PMID 30970626, 2019). "WNT signaling was found to be essential for the generation of cancer-initiating cells and two cancer stem cell markers—LGR5 and CD44—are known target genes of WNT signaling." (PMID 29652830, 2018). "In vitro studies demonstrated that cancer cells expressing CD44 and ALDH initiate more tumorspheres than CD44− and ALDH− cancer cells." (PMID 30380687, 2018). "As expected, we noted an upregulation of cancer stem cell markers LGR5 and CD44, as well as epithelial-to-mesenchymal transition marker ZEB1, in the spheroids." (PMID 29463813, 2018). "And as the key downstream effectors of OPN for cancer stemness, the expression levels of BMI1 and HIF1α were increased when DNMT1 was up-regulated in CD133+/CD44+ cells with shOPN." (PMID 30064482, 2018). "These cancer stem-like cells express important hepatic CSC markers such as CD24, CD44, CD117, CD133, ALDH, ABCG2, Oct4, and Nanog which were extensively reported before." (PMID 29848298, 2018). "The results revealed the expression of CD44, CD133, OCT-4, KLF4 and ABCG2 in the sphere forming cells and verified that cancer stem cells displaying the stemness properties were successfully isolated." (PMID 29559853, 2018).